VIM (vimentin)
Diseases named in the same sentence as VIM in open-access papers (continued):
Sharing a sentence is not in itself a finding about the gene and the disease.
colorectal cancer (continued). "In advanced colorectal cancers, vimentin is known to be frequently methylated, which is also used as a diagnostic tool here." (PMID 30248895, 2018). "BRD4 inhibition limited distal metastasis of colorectal cancer by regulating several key proteins including E-cadherin and Vimentin in the progression of EMT." (PMID 28545522, 2017). "PDGF-stimulated fibroblasts secrete stanniocalcin-1 and stimulate invasion of colorectal cancer cells through upregulation of VIM." (PMID 26954362, 2016). "Numerous studies described the vimentin reactive cells in benign and malignant breast tissues and vimentin expression in the tumour stroma was valuable in identifying colorectal cancer patients with a poor prognosis." (PMID 26640315, 2015). "This is underscored by an independent report finding vimentin methylation in only 72% of colorectal cancers and in as much as 11% of normal mucosa samples." (PMID 21777459, 2011). "Accordingly, we assessed the pattern of E-Cadherin and vimentin expression in colorectal cancer cell lines by western-blotting." (PMID 21747928, 2011). "More promising as a marker of neoplasia is vimentin promoter methylation, which is being evaluated as a candidate marker of colorectal carcinomas." (PMID 21448168, 2011). "Vimentin exon-1 sequences are methylated in most of colon cancer tissues and aberrant methylation of vimentin has become a novel molecular biomarker of colorectal cancer." (PMID 18445260, 2008). "Overall, our findings identify a novel TM9SF1-TRIM21-Vimentin-Tollip pathway involved in colorectal cancer metastasis, which may provide promising therapeutic targets for the treatment of metastatic colorectal cancer." (PMID 40175707, 2025). "Consequently, the downregulation of Vimentin results in a decreased number of F-actin-rich stress fibers and filopodium-like protrusions, ultimately inhibiting colorectal cancer metastasis." (PMID 40175707, 2025). "In colorectal cancer (CRC), the loss of PTPN23 leads to decreased expression of E-cadherin, along with upregulation of epithelial-mesenchymal transition (EMT) markers such as Vimentin and SNAIL, promoting cell migration." (PMID 40570022, 2025). "Besides, TGFβ1-induced FSTL1 binding to Vimentin activates focal adhesion signaling, promoting colorectal cancer cell migration, invasion, and metastasis." (PMID 38605354, 2024). "Finally, animal xenograft experiments and clinical colorectal cancer samples were used to study vimentin expression in tumor tissues." (PMID 37833712, 2023). "Furthermore, animal experiments and human colorectal cancer specimens have confirmed the nuclear translocation of vimentin." (PMID 37833712, 2023). "Furthermore, in colorectal cancer, SRGN transcriptional overexpression is associated with a mesenchymal phenotype, as N-cadherin and vimentin are upregulated and E-cadherin is downregulated through induction by the hypoxia-inducible factor 1a." (PMID 36358747, 2022). "Moreover, ARIH1 protein expression in colorectal cancer patients positively correlated with Vimentin protein expression and negatively correlated with E-cadherin, strengthening the link between ARIH1 and EMT induction in cancer." (PMID 35102251, 2022). "Additionally, exosomes derived from CD133+/CD44+ colorectal cancer cells after being transfected with sh-LINC01315 down-regulated BCL-2, MMP-9, and Vimentin, whereas up-regulated Bax, cleaved caspase-3, and E-cadherin in colorectal cancer cells (P < 0.05)." (PMID 35470736, 2022). "Another investigation discovered that CSDE1 could regulate the expression of c-Myc, Rac-1, PTEN, and vimentin in colorectal cancer." (PMID 35923244, 2022).
colorectal cancer (continued). "To confirm whether PGC-1α regulates the expression levels of LARS1, p-AKT, p-GSK-3β, p-mTOR, p-S6K1, p-4EBP1, β-catenin, c-Myc, cyclin D1, and vimentin in other colorectal cancer HT-29 and SNU-C4 cells, we performed qRT-PCR and Western blot analysis." (PMID 36612155, 2022). "The expression of VIM in colonic neoplastic cells is found to be correlated with the stage of neoplastic progression, which suggests that VIM is a key factor integrating epithelial to mesenchymal transition, and colonic neoplastic progression in colorectal cancer (CRC)." (PMID 34908921, 2021). "Vimentin methylation can be used as a biomarker for colorectal cancer." (PMID 32670437, 2020). "Vimentin gene methylation often occurs in advanced colorectal cancer." (PMID 32670437, 2020). "It remains unclear whether, and to what extent, vimentin expression correlates with intrinsic resistance to cisplatin in colorectal cancer." (PMID 32466394, 2020). "Vimentin (VIM) is considered a prognostic marker in colorectal cancer (CRC)." (PMID 30988394, 2019). "Furthermore, histone deacetylase inhibitor (HDACi)-resistant colorectal cancer cells show overexpression of vimentin compared to HDACi-sensitive colorectal cancer cells." (PMID 30248895, 2018). "Also, in colorectal cancer, expression of vimentin has been correlated to the stage of neoplastic progression of neoplastic cells." (PMID 30248895, 2018). "Consequently, we determined that colorectal cancer cells incubated in CC-MSCs-CM had elevated levels of vimentin and SLUG, and reduced levels of E-cadherin, which illustrated that CC-MSCs promote colorectal cancer metastasis via inducing ETM transition." (PMID 29348540, 2018). "In colorectal cancer, miR-378 may function as a tumor suppressor and plays an important role in inhibiting tumor growth and invasion by targeting vimentin." (PMID 30181714, 2018). "We aimed to explore the association between metformin treatment and epithelial-mesenchymal transition (EMT) phenotype and further appraise the prognostic values of metformin and EMT markers E-cadherin and vimentin for colorectal cancer (CRC) in clinical practice." (PMID 28744307, 2017). "In colorectal cancer H19 interacts with miR-200a and miR138 to boost Vimentin and ZEB1 expression." (PMID 28327666, 2017). "In order to clarify whether FAM83H translocates to nuclear speckles during EMT, we examined the expression of vimentin in colorectal cancer tissue showing the localization of FAM83H to nuclear speckles." (PMID 27681590, 2016). "Higher levels of stromal vimentin have been correlated with poor prognosis of colorectal cancer." (PMID 25852822, 2015). "It is known that the overexpression of VIM is significantly associated with HCC metastasis and it is a circulating molecular biomarker for HCC and that LASP-1 induces TGF-β-mediated EMT transition in human colorectal cancer." (PMID 25760690, 2015). "The association between vimentin and EMT in colorectal cancer cell was confirmed in a recent study." (PMID 21747928, 2011). "Furthermore, proteomic analysis identified the vimentin gene as one differentially expressed in colorectal cancer compared with the surrounding normal tissue." (PMID 17325702, 2007). "In this study, we evaluated the significance of vimentin expression in colorectal cancer (CRC)." (PMID 17325702, 2007). "Moreover, in colorectal cancer cells TEAD4 directly enhances the expression of Vimentin." (PMID 36186582, 2022). "To investigate any plausible contribution of Vimentin to 5-FU resistance in CRC, we treated a panel of three epithelial colorectal carcinoma cell lines (HCT-116, SW-620, and HT-29) with increasing concentrations of the said drug, transiently (24 h)." (PMID 33500399, 2021). "MiR-378 could inhibit tumor growth and invasion partly by targeting vimentin in colorectal cancer." (PMID 28289479, 2017).
colorectal cancer (continued). "After ARE combined with radiotherapy, β-Catenin was increased in human colorectal cancer HCT116 cells implanted in nude mice, while Vimentin was decreased." (PMID 41634588, 2026). "This aligns with findings in ovarian cancer, where HDAC4 silencing reduced cell migration, and in colorectal cancer, where NaB inhibited EMT via miR-200, increasing E-cadherin and reducing Snail and vimentin expressions." (PMID 40143970, 2025). "Our results indicate that CBD and radiation in combination reverse radioresistance in HCT116R and HT29R colorectal cancer cells by altering EMT characteristics, including elevated vimentin and N-cadherin expression and reduced E-cadherin expression." (PMID 41465451, 2025). "For example, TMEM97 silencing with siRNA increased E-cadherin but decreased N-cadherin and vimentin in HCT116/R and SW480/R colorectal cancer cell lines." (PMID 39995975, 2025). "The qRT-PCR results demonstrated that the mRNA levels of E-cadherin were reduced and the mRNA levels of N-cadherin and vimentin were increased in HCT116R and HT29R cells, indicating the change in the EMT phenotype in radio-resistant colorectal cancer cells." (PMID 41465451, 2025). "In three-dimensional colorectal cancer spheroids treated with PFOS, molecular analysis showed downregulation of E-cadherin and upregulation of N-cadherin and vimentin." (PMID 41441298, 2025). "Combining CBD with radiation sensitizes the radioresistant colorectal cancer cell lines HCT116R and HT29R through the modification of EMT markers, including E-cadherin, vimentin, and N-cadherin." (PMID 41465451, 2025). "Recently, it has been reported that over-expression of GLUT3 up-regulated EMT-related genes such as N-cadherin, Vimentin, and ZEB1 down-regulated the expression of E-cadherin in colorectal cancer." (PMID 38594707, 2024). "E-cadherin and vimentin are key molecules in the invasion of several tumors, such as HCC and colorectal cancer (CRC), playing important roles in tumor cell invasion." (PMID 38560575, 2024). "In a colorectal cancer liver metastasis mouse model, SHK treatment resulted in the EMT reversal as shown as the upregulated E-cadherin and the downregulated vimentin and α-SMA." (PMID 37161591, 2023). "Our preliminary studies also showed that IL-6 causes E-cadherin reduction and increases protein levels of twist, vimentin, snail, slug and α-SMA in HT-29 colorectal cancer cells." (PMID 37047623, 2023). "To investigate the mechanism of HMGB3 knockdown-mediated colorectal cancer inhibition, we detected that knockdown of HMGB3 decrease mesenchymal markers (N-cadherin, Vimentin) as well as the key factors of WNT/β-catenin signaling pathway (β-catenin)." (PMID 35712661, 2022). "As a pilot experiment to demonstrate MOSAICA’s potential for multiomics profiling, we utilized MOSAICA to detect 2 protein targets, Tubulin and Vimentin, and 2 mRNA targets, POLR2A and MTOR in colorectal cancer SW480 cell culture samples." (PMID 35013281, 2022). "In colorectal cancer, TRIM29‐overexpressed cells also showed VIM activation contributing to migration, invasion and metastases." (PMID 36420658, 2022). "Remarkably, it has been shown that in colorectal cancer cells TEAD4 promotes EMT in a YAP independent manner, regulating the expression of Vimentin." (PMID 36186582, 2022). "In colorectal cancer, microRNA-17-5p serves as a suppressor of EMT, through direct targeting of vimentin and inhibition of the Wnt pathway." (PMID 36230521, 2022). "In this study, colorectal cancer stem cell-derived exosomes promoted BCL-2, MMP-9 and Vimentin expressions, but inhibited those of E-cadherin, Bax and cleaved caspase-3." (PMID 35470736, 2022). "Blood samples of 316 colorectal cancer patients were used for CTC detection and subtyping with EpCAM, CK8/18/19, vimentin, and twist as biomarkers." (PMID 35493298, 2022).
colorectal cancer (continued). "For example, HIF-1α is upregulated in colorectal cancer cell lines and contributes to angiogenesis by modulating the expression of EMT-related molecules claudin-4, E-cadherin and Vimentin." (PMID 34036383, 2021). "EMT in lung and colorectal cancer is accompanied by induction of the expression of mesenchymal markers, including α-SMA and vimentin, and is thought to be a contributing source of myofibroblasts within fibrotic tissues." (PMID 33557232, 2021). "In contrast, overexpression of CLDN2 in colorectal cancer cells (HCT116CLND2‐GFP) revealed downregulation of E‐cadherin and upregulation of Collagen I, Fibronectin and Vimentin." (PMID 34965023, 2021). "The present study showed that E-cadherin (as an epithelial marker) is down-regulated whereas concomitantly N-cadherin, vimentin, and MMP-9 (as mesenchymal markers) are up-regulated in colorectal cancer." (PMID 34094030, 2021). "Fibronectin and vimentin are fibroblastic markers and play an important role in the process of EMT and tumorigenesis in colorectal carcinoma." (PMID 34527077, 2021). "The specific mechanism is the binding of EGF to EGFR, which activates downstream signaling pathways, leading to the downregulation of E-cadherin and upregulation of vimentin, thereby inducing EMT in colorectal cancer cells." (PMID 32148496, 2020). "In contrast, the hyperdiploid colorectal cancer cell line SW480, showed a marked decrease (~64%) in E-cadherin levels, but only a marginal increase in Vimentin levels." (PMID 32337580, 2020). "Earlier, YB-1 was shown to enhance vimentin expression and drive tumor progression via EMT in colorectal cancer." (PMID 33379356, 2020). "It has been observed that compound-11 induced downregulation of N-cadherin, vimentin and p-FAK (invasive marker), while E-cadherin was increased, through downregulation of Akt, which seems to be crucial for EMT in colorectal cancer cells." (PMID 30691229, 2019). "Overexpression of SPRY4-IT1 promoted EMT via the regulation of E-cadherin and vimentin expression in NSCLC cells, ESCC cells, colorectal cancer, and ovarian cancer cells." (PMID 29489909, 2018). "We found that E-cadherin and vimentin, two proteins frequently altered during epithelial–mesenchymal transition (EMT), was decreased and increased respectively in human colorectal cancer tissues, compared with the adjacent normal tissues." (PMID 29530061, 2018). "In colorectal cancer, where elevated HES1 expression is correlated with distal metastasis and poor prognosis, this protein enables upregulation of EMT markers like vimentin and N-cadherin, thereby promoting the invasive ability of cancer cells." (PMID 28122586, 2017). "We further showed that B7-H3 down-regulated the expression of E-cadherin and β-catenin and up-regulated N-cadherin and Vimentin expression, implying that B7-H3 promoted the EMT in colorectal cancer cells." (PMID 27145365, 2016). "As expected, we found that CD133+ cells in human colorectal cancer tissues had EMT phenotypes, downregulating E-cadherin and upregulating vimentin." (PMID 26284927, 2015). "Another novel marker, cell surface Vimentin (CSV), has recently been shown to detect EMT-positive CTCs in breast and colorectal cancer patients." (PMID 25986923, 2015). "In our study EMT was detected in samples of colorectal cancer based on coordinated changes in the expression of the following genes: ZEB1, ZEB2, SNAI1, CDH1, and VIM." (PMID 25157365, 2014). "In 2005, vimentin was licensed by the US Food and Drug Administration (FDA) for colorectal cancer (CRC) diagnosis." (PMID 24748968, 2014). "Then, we assessed the influence of TGFRI pharmacological inhibition on vimentin and E-cadherin levels in NRP2 expressing colorectal cancer cell lines." (PMID 21747928, 2011). "We performed immunostaining in 142 colorectal cancer (CRC) samples and quantified the amount of vimentin expression using computer-assisted image analysis." (PMID 17325702, 2007).
colorectal cancer (continued). "While trying to link CLP36 and EMT, it has been demonstrated that CLP36 could prevent metastatic potential or EMT of colorectal cancer cells, as seen by the elevated CDH1 expression and the diminished VIM, Snail and ZEB levels." (PMID 39735560, 2024). "Although one agonist, Olvanil, did not significantly increase vimentin expression, the other agonists increased vimentin expression in SW-620 colorectal cancer cells." (PMID 38534324, 2024). "Interestingly, we found that four of the markers best suited to distinguish cases from controls in our study were the already well-known colorectal cancer markers IKZF1, SFRP1, SFRP2 and VIM." (PMID 37438612, 2023). "It is worth noting that TEAD4 can regulate EMT and promote metastasis by directly transcribing vimentin without the binding with YAP in colorectal cancer, which is interesting." (PMID 35601657, 2022). "The overexpression of SDC2 in colorectal cancer results in induction of EMT and the upregulation of N-cadherin, Slug, Twist, vimentin, and MAPK signaling pathway activation, while SDC2 knockdown reduces cancer cell proliferation, migration, and invasion, and induces cell apoptosis." (PMID 36358747, 2022). "The COX‐2 selective antagonist celecoxib was revealed to prevent EMT‐mediated malignant transformation by modulating β‐catenin nuclear localization, the vimentin/E‐cadherin proportion and EMT‐TFs (Slug, Snail and ZEB1) in colorectal cancer cells and oral squamous cell carcinoma." (PMID 35601657, 2022). "The heavy metal cadmium (Cd) can promote the migration and invasion of colorectal cancer cells, and Cd could upregulate the expressions of N-cadherin, vimentin, and ZEB1 and downregulate the expression of E-cadherin in colorectal cancer cells." (PMID 35784761, 2022). "The overexpression of SALL4 was related to a poor prognosis, promoted the invasion and proliferation of colorectal cancer cells, and accelerated the occurrence of EMT, which was characterized by upregulation of Twist, vimentin, and N-cadherin expressions and downregulation of E-cadherin." (PMID 35692499, 2022). "To test our hypothesis, we cocultured IHH hepatocytes with HT29 colorectal cancer cells followed by immunofluorescence co-staining for EMT and motility biomarkers, using vimentin and actin-related protein 2/3 (ARP2/3), respectively." (PMID 35267627, 2022). "In colorectal cancer cells, knockdown of phosphoribosylaminoimidazole carboxylase, phosphoribosylaminoimidazole succinocarboxamide synthetase (PAICS) induced higher levels of E-cadherin and lower levels of vimentin." (PMID 34439333, 2021). "EGF was previously shown to regulate the EMT markers E-cadherin and Vimentin in mesothelioma cells and colorectal cancer cells but failed to do so in A549 cells." (PMID 33777943, 2021). "Based on the data of Dermani’s team, RES could inhibit EMT by enhancing miR-200c expression in colorectal cancer cells, its mechanism might be explained as targeting ZEB1 and vimentin expression." (PMID 33937049, 2021). "H19 may promote EMT by sponging miRNA-138 and miR-200a, and then upregulation of their downstream targets Vimentin,ZEB1 and ZEB2 in colorectal cancer." (PMID 33267897, 2020). "In colorectal cancers, overexpression of Cul4A induces the epithelial–mesenchymal transition through the regulation of H3K4 trimethylation at the E-cadherin, N-cadherin, and vimentin gene promoters." (PMID 31052599, 2019). "Vimentin is an important constituent of the cytoskeleton, whose expression goes up in many types of cancer during EMT and in the stromal cells of several cancers, such as non-small-cell lung cancer and colorectal cancer." (PMID 25852822, 2015). "Similarly, in patients with colorectal cancer, the novel marker Plastin3 identified the most aggressive CTCs undergoing EMT in one-third of 711 patients with colorectal cancers; these Plastin3-positive CTCs showed inducible staining of the EMT marker vimentin." (PMID 25986923, 2015).